TNFRSF10C (TNF receptor superfamily member 10c)
Description:
Acts as a receptor for the cytotoxic ligand TRAIL but does not contain the intracellular death domain required to initiate apoptosis. By competing with the functional TRAIL receptors TNFRSF10A and TNFRSF10B for ligand binding, it functions as a decoy receptor that protects cells from TRAIL-induced apoptosis.
Synonyms: DcR1; TRAIL-R3; CD263; LIT; TRAILR3; TRID; DCR1-TNFR
Tractability: Antibody: its Gene Ontology location is reachable by antibodies, with high confidence; UniProt places it where antibodies can reach, with medium confidence; UniProt predicts a signal peptide or a membrane-spanning region.
Gene: Protein-coding gene on chromosome 8 (23,102,921 to 23,118,759, forward strand). Ensembl gene ENSG00000173535.
Subcellular location: Cell membrane
Gene Ontology:
Molecular function: protein binding; receptor decoy activity; TRAIL binding
Cellular component: plasma membrane; cell surface
Genetic constraint (gnomAD): Loss-of-function variants: 11 observed, 12.32 expected, observed/expected ratio (o/e) 0.89, 90% interval 0.56 to 1.47. The synonymous counts are far from expectation, so gnomAD's model fits this gene poorly and the ratio says little. Missense variants: 207 observed, 315.2 expected, observed/expected ratio (o/e) 0.66, 90% interval 0.58 to 0.74. Synonymous variants: 57 observed, 108.83 expected, observed/expected ratio (o/e) 0.52, 90% interval 0.42 to 0.65.
Homologues: Orthologues: chimpanzee TNFRSF10C (97% identical), zebrafish tnfrsf1b (16% identical), zebrafish nradd (15% identical), mouse Tnfrsf26 (15% identical), rat Tnfrsf26 (15% identical), mouse Tnfrsf22 (14% identical), mouse Tnfrsf23 (14% identical), zebrafish tnfrsfa (14% identical), rat Tnfrsf22 (13% identical), tropical clawed frog nradd (13% identical), zebrafish hdr (13% identical), zebrafish cd40 (12% identical), and 2 more. Paralogues in human: TNFRSF10D (50% identical), TNFRSF10B (36% identical), TNFRSF10A (36% identical), TNFRSF21 (18% identical), LTBR (16% identical), TNFRSF1A (15% identical), TNFRSF4 (15% identical), FAS (15% identical), TNFRSF8 (15% identical), TNFRSF1B (14% identical), CD40 (14% identical), RELT (14% identical), and 9 more.
Diseases named in the same sentence as TNFRSF10C in open-access papers:
TNFRSF10C is named in the same sentence as 41 diseases in open-access papers, as found by Europe PMC text mining. Sharing a sentence is not in itself a finding about the gene and the disease. The quoted sentences say what the papers report.
breast carcinoma (6 papers, 2005 to 2021). "Although the function of LOC254896 remains to be clarified, the down-regulated expression and hypermethylation of TNFRSF10C in colorectal, prostate, and breast cancers has been reported previously." (PMID 32986753, 2020). "Through the TNFRSF10C and TNFRSF10D mRNA expression was inversely correlated with expression levels of miR-193 and miR-210 in breast cell lines and breast cancer patients, respectively." (PMID 33461524, 2021). "The TNFRSF10C and TNFRSF10D mRNA expression inversely correlated with the expression levels of miR-193 and miR210 in breast cell lines and breast cancer patients, respectively." (PMID 33461524, 2021).
pancreatic cancer (5 papers, 2012 to 2023). "Single investigated CpG of p16 (OR 10.4, 95%CI 2.0-54.7), BCL2 (OR 33.8, 95%CI 3.6-314.3), CD44 (OR 10.3, 95%CI 2.0-52.3) and TNFRSF10C (OR 11.8, 95%CI 2.2-64.1) were associated with pancreatic cancer." (PMID 22629410, 2012). "After treatment with 5-aza-dC and/or TSA, apoptosis was induced in pancreatic cancer cells to different degrees, and the levels of TNFRSF10C transcriptional expression in the pancreatic cancer cell lines increased markedly after 5-aza-dC treatment." (PMID 24084722, 2013). "We investigated methylation levels at selected CpG sites in the CpG rich regions at the promoter regions of p16, RARbeta, TNFRSF10C, APC, ACIN1, DAPK1, 3OST2, BCL2 and CD44 in the blood of 30 pancreatic tumor patients and in the blood of 49 matching controls." (PMID 22629410, 2012). "Moreover, RARbeta in blood correlated with TNFRSF10C, CD44, ACIN1, APC, p16 and LINE-1 in pancreatic tumor tissue." (PMID 22629410, 2012).
colorectal cancer (4 papers, 2013 to 2021). A primary or metastatic malignant neoplasm that affects the colon or rectum. "The copy number variation of TNFRSF10C and the downregulation of protein TNFRSF10C have been reported to be associated with colorectal cancer metastasis." (PMID 35111672, 2021). "Abnormal methylation of TNFRSF10C was found to be associated with different types of cancers, excluding colorectal cancer (CRC)." (PMID 30225159, 2018).
melanoma (3 papers, 2015 to 2023). A malignant, usually aggressive tumor composed of atypical, neoplastic melanocytes. "An increased production of the TRAIL-ligand TNFSF10 along with a decrease of the decoy receptor TNFRSF10c suggest that additional factors to DR5 could contribute to the improved apoptosis susceptibility of FKBP51-targeted melanoma cells." (PMID 34589486, 2021).
metastatic disease (2 papers, 2017 to 2021). "TNFRSF10C is a member of the TNF receptor superfamily, and studies have shown that TNFRSF10C CNV is related to distant metastatic disease." (PMID 34539886, 2021).
COVID-19 (1 paper, 2025). A disease caused by infection with severe acute respiratory syndrome coronavirus 2. "Further analysis of gene importance across the four models revealed that the top four hub genes in COVID-19 were CR1, TNFRSF10C, TAP2, and TGFBI, while the top four hub genes in SS-KCS were CR1, IL13, TAP2, and IL1R2." (PMID 40149556, 2025).
cutaneous leishmaniasis (1 paper, 2025). Leishmaniasis affecting the skin. "TNFRSF10C or TRAILR3 encodes the receptor for the apoptosis and pro-inflammatory response-inducing factor TRAIL, which has been associated with ulceration in cutaneous leishmaniasis." (PMID 40005779, 2025).
latent infection (1 paper, 2019). "The significant downregulation of TNFRSF10C could be a survival mechanism for M. tuberculosis during latent infection." (PMID 31921195, 2019).
Sepsis (1 paper, 2019). Sepsis is defined as life-threatening organ dysfunction caused by a dysregulated host response to infection. "On the other hand, TNFRSF10C, a downregulated gene has been shown to play an essential role in sepsis immune response." (PMID 31375728, 2019).
thyroid cancer (1 paper, 2024). "The results showed that eight key genes (NUAK2, TNFRSF10B, TNFRSF10C, TNFRSF12A, UNC5B, and PMAIP1) exhibited good diagnostic performance in differentiating between thyroid cancer patients and controls." (PMID 39104814, 2024). "TNFRSF10B, TNFRSF10C, TNFRSF12A, UNC5B, PMAIP1, and IL18 had increased expression in thyroid cancer tissues, while NUAK2 was decreased." (PMID 39104814, 2024). "Given that TNFRSF10B, TNFRSF10C and TNFRSF12A are up-regulated in thyroid cancer tissues and correlate with macrophages." (PMID 39104814, 2024).
triple-negative breast carcinoma (1 paper, 2021). An invasive breast carcinoma which is negative for expression of estrogen receptor (ER), progesterone receptor (PR), and human epidermal growth factor receptor 2 (HER2). "One publication reports that TNFRSF10C plays a role in triple-negative breast cancer cell survival and metastasis regulated by SOX9." (PMID 34256750, 2021).
tumor (33 papers, 2006 to 2026). "The expression of TNFRSF10C is often downregulated in tumor tissues, and a reduction in its copy number can promote distant metastasis in CRC30." (PMID 36646765, 2023). "Results showed that the relative expression of LEF1, VLDLR, RARRES2 and TNFRSF10C were significantly up-regulated compared to adjacent non-tumor tissues and other metastatic sites (P < 0.05)." (PMID 34256750, 2021). "In this study, we examined methylation patterns of ten tumor-associated genes (RASSF1A, GSTP1, RIZ1, SOCS1, TNFRSF10C, hTERT, NRG1, CLU, miR-203, miR-663) and of the LINE-1 repetitive element in 45 HCC and 17 matching non-tumor livers." (PMID 25889455, 2015). "Though TNFRSF10C is considered a ligand for apoptosis in several cancers, it also can promote tumor development and progression through activation of the NF-κB signaling pathway, which may explain its paradoxical protective effect in this cohort." (PMID 40011499, 2025). "At the same time, by inhibiting TNFRSF10C competitively binding with tumor necrosis factor-associated apoptosis-inducing ligand (TRAIL), TRAIL-induced tumor cell apoptosis can be promoted, thus possibly inhibiting the proliferation and metastasis of tumor cells." (PMID 36386893, 2022). "Similarly, analysis of TCGA database supported that TNFRSF10C was significantly hypermethylated in CRC tumor tissues." (PMID 30225159, 2018). "However, tumor cells often evade apoptosis through the overexpression of decoy receptors, such as TNFRSF10C, TNFRSF10D, and OPG, which activate pro-survival pathways like NF-κB and contribute to metastasis and therapy resistance in many cancers, including in EOC." (PMID 40943317, 2025). "Yet, the mechanism of TNFRSF10C downregulation, which is linked to the development of carcinogenic tissue, is not of direct relevance here as hypermethylation was observed in the blood surrogate tissue and not the tumor tissue itself." (PMID 22629410, 2012). "All of these genes are known to be involved in different aspects of breast carcinogenesis, which includes tumor suppression, HIC1, CDH1, CDH13, CDKN2, DNA repair, MGMT, apoptosis, PYCARD, TNFRSF10C, and cell cycle regulation, CCNA1." (PMID 25403427, 2014).
cancer (16 papers, 2009 to 2025). A tumor composed of atypical neoplastic, often pleomorphic cells that invade other tissues. "As a TRAIL receptor, TNFRSF10C primarily activates the NF-κb pathway of cancer cells (Murphy, Perry & Lawler, 2008)." (PMID 30225159, 2018). "Although it remains unclear whether TNFRSF10C plays a pro-apoptotic or an anti-apoptotic role in tumors, hypermethylation of TNFRSF10C has been reported in various human cancers." (PMID 22629410, 2012). "However, there are two potential mechanisms of TNFRSF10C in the pathogenesis of cancer." (PMID 30225159, 2018). "A total of 8 cancer genes with an OncoScore above the 90th percentile was identified (TNFRSF10B, TNFRSF10C, TNFRSF10A, TNFRSF10D, LZTS1, NKX3-1, BNIP3L and RHOBTB2; OncoScore range: 71.4–86.3)." (PMID 28387367, 2017). "TNFRSF10C, an antagonistic receptor protecting cells from TRAIL-induced apoptosis, is an example, and its genomic deletion and promoter hypermethylation have been found in a variety of cancers, including pancreatic, prostate, colon, lung, breast, bladder cancers." (PMID 39323623, 2024).
TNFRSF10C also shares sentences with these, for which no sentence is quoted: ovarian carcinoma (2 papers); adenoma (1); Ascites (1); bladder cancer (1); cerebral aneurysm (1); childhood asthma (1); colon cancers (1); colorectal (1); esophageal cancer (1); gastric cancer (1); glioblastoma (1); glioma (1); hepatic carcinoma (1); hepatitis B (1); Hypermetropia (1); infection (1); invasive breast carcinoma (1); invasive ductal carcinoma (1); liver diseases (1); lung carcinoma (1); myeloma (1); myopia (1); osteosarcoma (1); pancreatic adenocarcinoma (1); Parkinson disease (1); prostate tumor (1); rheumatoid arthritis (1); type 1 diabetes mellitus (1).